MTHFD2 (methylenetetrahydrofolate dehydrogenase (NADP+ dependent) 2, methenyltetrahydrofolate cyclohydrolase)
Diseases named in the same sentence as MTHFD2 in open-access papers (continued):
Sharing a sentence is not in itself a finding about the gene and the disease.
cancer (continued). "Within mitochondrial folate one-carbon metabolism, the enzyme MTHFD2 has attracted considerable attention as a potential target for cancer therapeutics, motivated by a favorable expression profile with high expression in various human tumor types but low or undetectable levels in most adult tissues." (PMID 30275950, 2018). "In both cancers, patients with high MTHFD2 expression had a poor prognosis." (PMID 30582043, 2018). "MTHFD2 has potential for cancer therapy as a promising drug discovery target compared with SHMT2." (PMID 30582043, 2018). "The results clarified that MTHFD2 was enhanced in most cancers." (PMID 30582043, 2018). "Likewise, enhanced expression of MTHFD2 in cancer cells is predicted to enable increased flux through the mitochondrial 1C metabolic pathway, enabling unregulated proliferation." (PMID 29225823, 2017). "Since carolacton is able to inhibit both reactions carried out by this enzyme and perturbs cofactor binding, we believe that carolacton, a non-substrate inhibitor, may be used as a tool compound to assess MTHFD2 as an anti-cancer target in the future." (PMID 29142318, 2017). "As mitochondrial MTHFD2 is known to be upregulated in cancer cells, it may be possible to use carolacton as an inhibitor tool compound to assess MTHFD2 as an anti-cancer target." (PMID 29142318, 2017). "MTHFD2 is broadly required for cancer cell proliferation and viability." (PMID 28210221, 2017). "Moreover, the important roles of MTHFD2 in cell proliferation, DNA synthesis control, and cell migration in cancer have been confirmed." (PMID 29312619, 2017). "Altogether, MTHFD2 is an attractive candidate drug target in cancer." (PMID 26461067, 2015). "However, there are many mechanisms by which a protein can affect overall culture growth, and further work is needed to provide mechanistic insight into how the MTHFD2 protein influences cancer cell proliferation." (PMID 26461067, 2015). "This new role for MTHFD2 adds to its known mitochondrial function that provides one-carbon units for nucleotide synthesis and other methylation reactions, and further implicates MTHFD2 as a key protein for cancer cell proliferation." (PMID 26461067, 2015). "Hence, the MTHFD2 protein is capable of driving cancer cell proliferation independently of its dehydrogenase activity." (PMID 26461067, 2015). "Additionally, silencing of MTHFD2 using RNAi was lethal to cancer cell lines." (PMID 41303507, 2025). "Finally, an additional complication for cancer therapy is the potential detrimental effect of MTHFD2 on the immune system, as we will see in Section 6, that could counter the benefits of targeting this enzyme in cancer cells." (PMID 41303507, 2025). "The emphasis on the oncogenic role of MTHFD2 and its potential as a novel drug target has inadvertently led to reduced attention given to the emerging recognition of this enzyme also having important function in non-cancer cells, especially in the immune system." (PMID 41303507, 2025). "In addition, MTHFD2 may promote tumor progression by protecting cancer cells from oxidative stress, since MTHFD2 is a NADP+/NAD+-dependent enzyme that regulates the NADP+/NADPH and NAD+/NADH ratios." (PMID 40604332, 2024). "Finally, MTHFD2 may contribute to cancer cell survival through other mechanisms, such as the regulation of the immune response or promotion of drug resistance." (PMID 40604332, 2024). "Consequently, cancer cells undergo cell death despite high MTHFD2 expression." (PMID 39668825, 2024). "The canonical mitochondrial function of MTHFD2 could support tumor progression by providing substrates for the de novo synthesis of nucleotide precursors needed for the rapid DNA replication required by cancer cells." (PMID 40604332, 2024).
cancer (continued). "As TH9619 exerts different effects on 1C metabolism flux in MTHFD2-expressing versus null cancers, we next explored whether these distinct metabolic changes also result in different biological effects in these cells and how hypoxanthine contributes to sensitization." (PMID 37012496, 2023). "Notably, THCA, LIHC, KIRP, KIRC, KICH, and BLCA reached significance in almost all co-expression analysis and immune cell infiltration analysis, indicating that these cancers may be a suitable candidate for MTHFD2-based therapy or predictive model." (PMID 38130721, 2023). "The results showed that MTHFD2 may be involved in various intracellular tumor-related biological processes including the cell cycle, DNA mismatch repair, DNA replication, cancer pathways, methionine metabolism, and Wnt, MAPK, PI3K-AKT, JAK-STAT, and NF-κB signaling pathway activation." (PMID 36726381, 2023). "Thus, the substrate (THF)-binding activity is key for MTHFD2-mediated cancer cell proliferation." (PMID 35228749, 2022). "Hence, although the MTHFD2-dependent mitochondrial pathway to generate formate is the default route in most cancer cells, the cells can probably switch to use cytosolic pathways under certain conditions, such as survival selection pressure on MTHFD2 deletion by CRISPR–Cas9." (PMID 35228749, 2022). "MTHFD2 is broadly required for cancer cell proliferation and viability as a metabolic enzyme and was overexpressed around the tumor regions with poor nutrient access in GBM patients, and the suppression of MTHFD2 could cause cancer cell death." (PMID 35429411, 2022). "Moreover, we noticed that approximately 20% of the responding cancer cells consistently survived despite increasing concentrations of MTHFD2 inhibitors, which could be related to earlier observations that MTHFD2 knockdown induces AML differentiation." (PMID 35228749, 2022). "Induction of the onco-metabolic enzyme MTHFD2, which has been shown here to promote tumor development in both immune-dependent and -independent ways, may be a major cause of the pro-tumor effect of IFN-γ in cancer treatment." (PMID 33782411, 2021). "Therefore, combining IFN-γ with a strategy to inhibit tumor-expressed MTHFD2 may offer a better approach to cancer immunotherapy." (PMID 33782411, 2021). "Due to its absence in most adult tissues, MTHFD2 may be a safe target for cancer therapy." (PMID 33782411, 2021). "Similarly, other studies also reported that MTHFD2 could modulate cancer cell migration and invasion through regulating EMT-related proteins." (PMID 32759461, 2020). "We also determined that whether MTHFD2 knockdown may influence cancer initiating ability." (PMID 32759461, 2020). "How MTHFD2 might promote cancer progression remains undetermined." (PMID 32411609, 2020). "Thus, MTHFD2-mediated mitochondrial 1C metabolism may be a general mechanism involved in the maintenance of stemness in cancer cells." (PMID 30532069, 2019). "Thus, cancer cells with acquired resistance to molecular targeted therapies may depend on MTHFD2 for growth in general." (PMID 30532069, 2019). "Thus, cancer cells appear to be more dependent on MTHFD2 for growth than normal cells." (PMID 30532069, 2019). "We next examined whether MTHFD2 confers cancer stem-like properties." (PMID 30532069, 2019). "We next evaluated whether MTHFD2 was required for the growth of drug-resistant cancer cells." (PMID 30532069, 2019). "Therefore, we focused on MTHFD2, which is highly expressed in cancer cells." (PMID 30582043, 2018). "In addition, these candidate compounds decreased levels of MTHFD2 metabolites in cancer cells." (PMID 30582043, 2018). "Since MTHFD2 is involved in redox, these cancers may adapt to hypoxia by enhancing MTHFD2." (PMID 30582043, 2018). "Therefore, MTHFD2 inhibitors represent a promising candidate for cancer therapy." (PMID 30582043, 2018). "Finally, we assessed whether nuclear localization of MTHFD2 also occurs in cancer cells in human tumors." (PMID 26461067, 2015).
cancer (continued). "Folate metabolism can produce mitochondrial NADPH through ALDH1L2 and potential MTHFD2, and the knockdown of SHMT2 in some cancer cell lines increases their vulnerability to oxidative stressors." (PMID 37147729, 2023). "Moreover, MTHFD2 was discovered to be positively associated with several immune checkpoints, such as cytotoxic T lymphocyte-associated antigen-4 (CTLA-4), PD-L1, T-cell immunoglobulin and mucin domain-3 (TIM-3), and Programmed Cell Death 1 (PD-1) in most cancers, especially in BLCA." (PMID 38130721, 2023). "Although some MTHFD2 inhibitors were reported, only two compounds, LY345899 and DS18561882, showed anti-cancer activity in vitro and in vivo." (PMID 37664062, 2023). "Inhibition of MTHFD2 leads to imbalance of NADPH and redox homeostasis, which inhibits tumorigenic proliferation and growth, and increases cancer cell death under hypoxia." (PMID 37936908, 2023). "Many one carbon metabolic enzymes, including SHMT2, MTHFD2, and ALDH1L2, are highly expressed in human cancers, but how their activities are regulated is poorly understood." (PMID 37507016, 2023). "We propose that MTHFD2 is crucial for sustaining the production of CH2-THF, generated as a substrate for TYMS in cancer cells." (PMID 35228749, 2022). "This is in sharp contrast to what is observed by MTHFD2 CRISPR‐Cas9 KO, where cancer cells survive by activating the serine hydroxymethyltransferase 1 (SHMT1) pathway." (PMID 35583750, 2022). "In accordance with the observations using MTHFD2 RNAi19, our MTHFD2 inhibitors also induced AML differentiation and cancer cell death in a dose- and time-dependent manner." (PMID 35228749, 2022). "Two such mitochondrial proteins, MTHFD2 and SHMT2, are among the most differentially expressed metabolic enzymes in cancer cells compared to normal cells." (PMID 34341479, 2022). "We also show that CRISPR–Cas9 MTHFD2−/− knockout cancer cells and clones are significantly more resistant to TH9619 compared with the parental WT cells, demonstrating that inhibition of MTHFD2 is necessary for the efficacy of TH9619 in cancer cells." (PMID 35228749, 2022). "Similar studies on the mitochondrial folate metabolism enzymes revealed a link between cancer and aberrant SHMT2 and MTHFD2 expression." (PMID 36551330, 2022). "These MTHFD2 inhibitors are largely selective, engage with the target in cells and tumors, and effectively block proliferation of AML cancer in vitro and in vivo, with a therapeutic window spanning several orders of magnitude." (PMID 35228749, 2022). "TPA-associated genes differentially expressed in the Bhas 42 CTA included markers such as RAN, MTHFD2, WT1, and AURORA-A, which lead to carcinoma formation and malignant transformation in humans and test animals." (PMID 35328637, 2022). "Since epithelial‐mesenchymal transition (EMT) serves as a well‐known mechanism involved in cancer metastasis, we then investigated the alteration of common EMT markers by MTHFD2." (PMID 34121323, 2021). "As a downstream player in the folate pathway, one-carbon metabolism, including serine and glycine, is activated in many cancer cells, with high levels of the mitochondrial enzyme genes SHMT2 and MTHFD2." (PMID 33468252, 2021). "Interestingly, among 1454 metabolic enzymes differentially expressed in cancer tissues, enzymes involved in the folate pathway were found to be amongst the most differentially expressed genes between cancers and normal cells, with MTHFD2 ranking at the top of the list." (PMID 34445444, 2021). "MTHFD2 knockdown or treatment with AICAR reduced the stem-like properties and restored gefitinib sensitivity in these gefitinib-resistant cancer cells." (PMID 30532069, 2019). "Collectively, these results confirmed that MTHFD2 was upregulated upon EGF stimulation in some normal and cancer cells." (PMID 30532069, 2019). "However, recent evidence suggests that MTHFD2 has a non-enzymatic function which may underlie the dependence of cancer cells on this protein." (PMID 30275950, 2018).
cancer (continued). "The MTHFD2 in GSE21050 is seen as a prognostic factor and a potential therapeutic target for future cancer treatments." (PMID 30158596, 2018). "We also noted a concerted induction of the D2PPI proteins in stimulated T cells, in line with previous observations of MTHFD2 induction in this setting, and also suppression of D2PPI genes in HCT-116 cancer cells in response to treatment with a CDK inhibitor." (PMID 30275950, 2018). "The integrated analysis identified glycine consumption as well as expression of the mitochondrial glycine biosynthetic pathway (SHMT2, MTHFD2 and MTHFD1L) to be strongly correlated with the rates of proliferation across all cancer cell lines." (PMID 28177894, 2017). "Another enzyme located in the mitochondria, methylene-tetrahydrofolate dehydrogenase 2 (MTHFD2), which uses NAD+ as a coenzyme, is overexpressed in rapidly proliferating malignant tumors." (PMID 26907355, 2016). "Examination of the gene expression of 1425 metabolic enzymes across NCI-60 cancer cell lines revealed that enzymes of glycine metabolism (including SHMT2, MTHFD2 and MTHFD1L) are highly expressed in rapidly-proliferating cancer cells." (PMID 27391339, 2016). "Three enzymes (MTHFD2, ATIC, and SHMT2) in this pathway were found to be overexpressed in many cancers." (PMID 25243088, 2014). "Cancer cells display a certain degree of metabolic plasticity with enhanced cytosolic 1C flux, mitochondria also possess a paralog enzyme, and MTHFD2 has additional non-metabolic functions." (PMID 41303507, 2025). "Depletion of MTHFD2 abolishes IR‐induced recruitment of RPA and RAD51 into repair foci, blocks HR activity and ultimately results in a high amount of unresolved DSBs and accumulation of cancer cells in G2/M phase." (PMID 38533616, 2024). "Besides, MTHFD2 increased NADH production in both normal and cancer cells when respiration was impaired, either by oxygen deprivation or by inhibition of electron transport chain activity." (PMID 40604332, 2024). "Challengingly, they also demonstrated strong inhibition of the MTHFD1 and MTHFD2L isoforms, which are expressed in healthy adult human tissues, unlike MTHFD2 that is explicitly expressed in several cancer cells." (PMID 39256448, 2024). "Another concern is that, while MTHFD2 depletion appears to inhibit tumor growth, it is not sufficient to kill cancer cells." (PMID 40604332, 2024). "To validate the impressive results of MTHFD2 transcript, we investigated the protein pattern in 117 RCC tissues through immunohistochemistry, which is a low-cost method used to complement pathological diagnosis of cancer." (PMID 38422037, 2024). "The fact that mitochondrial MTHFD2 is required for mediating TH9619 inhibitor’s toxicity in cancer cells explain why these inhibitors do not have adverse effects in normal cells, where MTHFD2 is weak or not expressed." (PMID 40604332, 2024). "Additionally, we noted that MTHFD2 expression was correlated with TMB and MSI in several cancers, indicating its potential value for predicting immunotherapy response in these cancers." (PMID 38130721, 2023). "Methylenetetrahydrofolate dehydrogenase (MTHFD2) is a mitochondrial enzyme involved in 1 C metabolism that is upregulated in various cancer cells, but absent in normal proliferating cells." (PMID 37129313, 2023). "However, a negative correlation with immunoregulators was also observed in some cancers, including DLBC, LUAD, LUSC, and TGCT, reflecting the high heterogeneity of MTHFD2 function in various cancers." (PMID 38130721, 2023). "Cancer cells fuel their increased need for nucleotide supply by upregulating one-carbon (1C) metabolism, including the enzymes methylenetetrahydrofolate dehydrogenase–cyclohydrolase 1 and 2 (MTHFD1 and MTHFD2)." (PMID 37012496, 2023). "Although MTX and VE-821 significantly blocked DNA RF progression in both cancer and nontumorigenic cells, MTHFD2 inhibitors effectively impaired DNA replication only in AML cells, sparing nontumorigenic lymphocytes." (PMID 35228749, 2022).
cancer (continued). "The specific mechanism of action of MTHFD2 inhibitors presumably also explains their high tolerability and lack of general efficacy across many cancer cell lines." (PMID 35228749, 2022). "Targeting MTHFD2 has become an important strategy in eradicating cancer cells without damaging normal cells." (PMID 35613161, 2022). "The DepMap database of CRISPR‐Cas9 KO cells supports that MTHFD2 is not required for cancer cell survival." (PMID 35583750, 2022). "The folate metabolism enzyme MTHFD2 (methylenetetrahydrofolate dehydrogenase/cyclohydrolase) is consistently overexpressed in cancer but its roles are not fully characterized, and current candidate inhibitors have limited potency for clinical development." (PMID 35228749, 2022). "MTHFD2, an essential enzyme in this one carbon metabolic pathway which is upregulated in various cancer cells including LUAD, plays important roles in cancer cells growth and is responsible for poor prognosis of many cancer types." (PMID 35790743, 2022). "NADPH-producing mitochondrial one-carbon metabolism protein methylenetetrahydrofolate dehydrogenase (NADP+ dependent) 2 (MTHFD2) was shown to be substantially expressed in 19 distinct cancer types, but not in normal adult proliferating cells." (PMID 36358687, 2022). "Furthermore, a number of cancer-related pathways were enriched in MTHFD2 high group, including NF-κB activation, JAK/STAT, and cancer immunotherapy by PD1 blockade." (PMID 35581573, 2022). "Methylenetetrahydrofolate dehydrogenase 2 (MTHFD2) is a mitochondrial 1‐carbon metabolism enzyme, which is an attractive anticancer drug target as it is highly upregulated in cancer but is not expressed in healthy adult cells." (PMID 35712863, 2022). "We confirm previously published cancer dependency on MTHFD2 for cancer cell proliferation using an RNAi approach, and show that WT, but not catalytically dead, RNAi-resistant MTHFD2 can rescue cytotoxicity on MTHFD2 silencing." (PMID 35228749, 2022). "Although MTHFD2 RNA interference (RNAi) knockdown has been shown to block proliferation of cancer cells, these experiments have not been complemented with rescue expression of RNAi-resistant MTHFD2." (PMID 35228749, 2022). "In addition, PD-L1 mRNA and protein, as well as both O-GlcNAcylated and total cMYC proteins, were suppressed by MTHFD2-KD and recovered by exogenous UTP/UDP in cMYC-overexpressing cancer cells, all of which were compromised in MYC-T58A-overexpressing cells." (PMID 33782411, 2021). "Their high levels of expression in cancer cells may reflect their regulation by MYC as MYC binds to the SHMT2 and MTHFD2 gene promoters, along with that for MTHFD1L." (PMID 35008360, 2021). "Besides, MTHFD2 knockdown diminished N‐cadherin and vimentin expression in LUAD cells since EMT is a fundamental property for cancer metastasis." (PMID 34121323, 2021). "In this context, MTHFD2, which is rarely expressed in normal adult tissues, where it has a functional substitute in MTHFD2L, may well be a safe therapeutic target for cancer treatment." (PMID 33782411, 2021). "Our results indicated that folic acid inhibited the expression of MTHFD2 and NID1, speculating that folic acid may inhibit the expression of MTHFD2 and NID1, and it may be used in cancer treatment in the future." (PMID 34604366, 2021). "A better understanding of both the enzymatic and non-enzymatic functional roles of MTHFD2 is essential for the optimal targeting of this novel candidate in cancer therapy." (PMID 32411609, 2020). "The bifunctional methylenetetrahydrofolate dehydrogenase/cyclohydrolase (MTHFD2) is a mitochondrial one-carbon folate metabolic enzyme whose role in cancer was not known until recently." (PMID 32411609, 2020). "Recent reports have indicated the role of highly expressed methylenetetrahydrofolate dehydrogenase 2 (MTHFD2) enzyme in cancers, showing poor survival; however, detailed mechanistic insight of metabolic functions of MTHFD2 have not been well-defined." (PMID 32759461, 2020).